VDR (vitamin D receptor)
Diseases named in the same sentence as VDR in open-access papers (continued):
Sharing a sentence is not in itself a finding about the gene and the disease.
cancer (continued). "Delving into the mechanisms of calcitriol/VDR modes of action, our transcriptome analysis revealed that several genes regulated by calcitriol administration are participating in biological processes related to cell migration and motility, both mandatory for cancer progression." (PMID 33466695, 2021). "We analyzed VDR after treatment with a physiological dose of vitamin (minimum limit, 100 nM), and with a high dose (about 10% above maximum limit, 400 nM), considering the possibility that cancer cells could be resistant to 1α,25(OH)2VD3 treatment." (PMID 33126474, 2020). "Moreover, vitamin D resistance may occur during cancer progression due to epigenetic changes in the VDR gene or expression of other genes including CYP24A1." (PMID 32456160, 2020). "In addition to its nuclear localization, VDR has been recently localized in mitochondria and calcitriol was found to suppress mitochondrial respiration in cancer cell lines, keratinocytes and adipocytes, affecting both cell growth and differentiation, as well as lipid metabolism." (PMID 33133014, 2020). "VDR belongs to the steroid hormone receptor superfamily and participates in many biological processes, such as cell proliferation, differentiation, apoptosis and immune response; significantly low expressions of VDR have been demonstrated in a variety of malignant tumors including CRC." (PMID 33817215, 2020). "Therefore, whether benefits from vitamin D supplementation for the prevention of cancer vary according to vitamin D receptor genotype is unknown and warrants further investigation." (PMID 31466528, 2019). "In addition to the contribution to ADME gene regulation, VDR also exerts an effect on cancer biology and the cell proliferation capacity, which could explain its impact on patient survival." (PMID 31850208, 2019). "We found that calcitriol treatment increased expression of IGFBP5 in bulk cancer cells, while decreased its expression in CSCs, suggesting that differential induction of IGFBP5 by calcitriol could be a reason for differential activation of VDR signaling in CSCs and bulk cancer cells." (PMID 29581858, 2018). "Since its function as cell cycle regulator involve miRNAs in diverse types of cancers, vitamin D receptor pathways gaining cePathway relationships to 23 cell cycle checkpoint pathways may enhance the antiproliferative and cell cycle arrest mechanisms at the ceRNA level." (PMID 29565967, 2018). "Furthermore, vitamin D could be critical in preventing cancer progression and thus cancer cells may actively counteract the tumor-suppressive effects of vitamin D by developing multiple mechanisms to abrogate VDR expression, as well as its activity." (PMID 29657326, 2018). "Moreover, the metabolites produced from the CYP11A1-driven alternative vitamin D metabolism pathway have been shown to be a biased agonist of VDR with less calcemic effect while retaining anti-proliferative properties in cancer comparable to those of calcitriol." (PMID 29657326, 2018). "Importantly, they showed that there are sustained levels of the VDR in both normal and cancer-associated PSCs, which was previously not known to be the case for the exocrine pancreas." (PMID 30400571, 2018). "Indeed, stabilizing β-catenin in VDR-KD cells partially restored the growth of these cancer cells." (PMID 28944088, 2017). "The purpose of up regulating the expression of VDR by VDR agonist is mainly used to inhibit inflammatory reactions; such as inhibiting peritoneal inflammation by the inhibition of macrophage recruitment and inflammatory cytokine secretion, inhibiting chronic inflammation and anti-cancer." (PMID 28881831, 2017). "Thus, VDR status can be a double-edge sword in relation to cancer." (PMID 28427151, 2017). "Therefore, in order to evaluate whether LSD1 and VDR regulate the methylation status of other cancer-related genes, a PCR array containing methylation-specific probes for 94 genes involved with PCa progression was used." (PMID 28811844, 2017).
cancer (continued). "Although vitamin D possesses anti-cancer properties and 1,25D has been reported to promote the differentiation or death of cancer cells (and references therein), there is evidence that also supports an anti-apoptotic function of the VDR, independently of 1,25D." (PMID 26950144, 2016). "Over 60 single nucleotide polymorphisms (SNPs) of the VDR gene located in the promoter region, in exons 2–9, and their vicinity, as well as in the 3′UTR region, that modulate its activity have been described and some of them have been studied in relation to cancer susceptibility and prognosis." (PMID 25195132, 2014). "The molecular interplay between cytokine signaling, VDR expression, genetic variability in patients with myopathy due to chronic inflammatory conditions such as cancer cachexia may reveal the molecular basis for changes that have been observed in skeletal and cardiac muscle." (PMID 24782788, 2014). "Given that normal mammary cells utilize 25(OH)D3 as substrate for local tissue generation of 1,25(OH)2D3, imbalanced expression of either CYP24A1 or CYP27B1 favoring catabolism could theoretically contribute to escape of developing tumor cells from anti-cancer VDR signaling." (PMID 24982636, 2014). "Therefore, our combined data from VDR knock out as well as VDR OE experiments in SKBR3 cells clearly suggest that manipulation of VDR expression dictates the ability of cancer cells to form mammospheres by regulation of Snail/E-cad-mediated pathway, which is essential during EMT process." (PMID 23341935, 2013). "Likewise, enhanced antiproliferative effects of 1,25D combinations with the soy isoflavone genistein or the RRR stereoisomer of α-tocopherol in nonleukemic cancer cells were associated with elevated VDR expression." (PMID 23259067, 2012). "In this study, we found that the VDR FokI T/T genotype was associated with a poor progression-free survival rate in patients with HNSCC, even after adjusting for age, gender, smoking status, primary tumor site, cancer stage, residual tumor, and postoperative treatment (chemotherapy or radiotherapy)." (PMID 22242137, 2011). "Vitamin D's antiprostate cancer activities may be involved in the actions through the pathways mediated by vitamin D metabolites, vitamin D metabolizing enzymes, vitamin D receptor (VDR), and VDR-regulated genes." (PMID 21991434, 2011). "Furthermore, discovery of VDR expression in diverse normal human tissues including B and T lymphocytes, the hair follicle, muscle, adipose tissue, bone marrow and in cancer cells has widened the perceived scope of the vitamin D endocrine system, beyond bone homeostasis." (PMID 19737544, 2010). "Thus, being the VDR mostly expressed in ER-positive carcinomas, Vitamin D or its analogues may become an alternative therapy for these tumours in cases of resistance to ER-targeted therapy." (PMID 20831823, 2010). "It appeared in different cancer datasets, specifically in THB (P10828), VDR (P11473), NR1D1 (P20393), and RORA (P35398)." (PMID 40334012, 2025). "The anti-cancer effects of VD were further validated in colorectal cancer (CRC), where VDR expression in tumor stromal fibroblasts was found to be associated with better overall survival and progression free survival." (PMID 41374952, 2025). "These microbiota-shaped BAs, by engaging a repertoire of host receptors—including FXR, TGR5, VDR, and S1PR2—on immune, stromal, and cancer cells, collectively orchestrate a complex signaling network." (PMID 40821794, 2025). "Recent studies emphasize the role of the vitamin D receptor (VDR) in regulating cell differentiation and stemness in various types of cancer." (PMID 40332380, 2025). "Specifically, VDR expression was significantly upregulated in CESC across all age groups, races, and cancer stages." (PMID 39268267, 2024).
cancer (continued). "Injury-induced populations were highest for TFs related to cell proliferation, self-renewal, and cancer involving both intrinsic (E2F family, MYC, and ZFX) and extrinsic (HIF1a, EPAS1/HIF2a, NFYB, LEF1, GLI2, VDR, and SMAD1/3/5) pathways." (PMID 38905342, 2024). "We explored the relationships between VDR expression and prognosis, immune infiltration, tumor microenvironment, or gene set enrichment analysis (GSEA) in 33 types of human cancers based on multiple public databases and R software." (PMID 38639057, 2024). "Our previous published studies have shown that VDR overexpression in PAAD cells inhibits stemness and sensitizes cancer cells to gemcitabine." (PMID 38600588, 2024). "Due to the dysregulation of the VDR, AMP expression levels alter, and cancer biology is influenced through altered DNA methylation patterns." (PMID 37317103, 2023). "Strategies to maintain VDR expression in CRC patients are promising to prevent and treat cancers in the future." (PMID 37046222, 2023). "Vitamin D (VD) via stimulation of Vitamin D receptor (VDR) plays an important role in BC development, modulating cancer cell proliferation, differentiation, apoptosis, and epithelial–mesenchymal transition, as shown in preclinical and clinical studies." (PMID 37755276, 2023). "The cancer progression in xenograft mouse models correlated to the elevation of LSD1 and VDR protein levels." (PMID 38274206, 2023). "For instance, TRPV6, the epithelial Ca2+ channel modulated by the vitamin D receptor, has also been previously related to CRC and other forms of cancer." (PMID 36900391, 2023). "Collectively, by identifying, for the first time, the VDR/BIM axis, we here provide a molecular rationale for the reported anti-cancer activity of VitD/analogs in combination therapies." (PMID 36291915, 2022). "Thus, a low VDR expression may be a prognostic marker for cancer development and progression." (PMID 36362766, 2022). "In CRC, the SNP rs11064124G > A in a cancer-specific SE at 12p13.31 promotes its binding affinity to vitamin D receptor (VDR), resulting in the greatly reduced expression of the tumor suppressor genes CD9 and PLEKHG6, which leads to cancer cell proliferation." (PMID 35277481, 2022). "Collectively, the VDR and CYP24A1 were widely expressed in a multitude of bone metastases, pointing to a potential role of vitamin D signalling in cancer progression." (PMID 36362766, 2022). "We consider the likely biological determinants of cancer outcome, the reported effects of vitamin D3 on these in both cancerous and non‐cancerous settings, and how the effect of vitamin D3 might change depending on the integrity of tumour vitamin D receptor (VDR) signalling." (PMID 35445563, 2022). "On the other hand, H. parainfluenza also upregauted VDR/RXR signaling in SCC4, which has potential to control cancer cell growth by driving anti-proliferative pathways and by enhancing adhesion." (PMID 35600164, 2022). "By inhibiting the Wnt/β-catenin signaling pathway, active vitamin D metabolites can limit cancer cell proliferation and promote the transformation of CRC cells expressing VDR into the epithelial cells." (PMID 36014889, 2022). "By identifying the VDR/VitD/BIM axis, we here provide a molecular rationale for the anti-cancer activity of VitD/analogs in combination therapies, which should be further exploited in the clinics." (PMID 36291915, 2022). "Multiple preclinical studies have demonstrated that vitamin D receptor (VDR), a nuclear receptor that modulates transcription of target genes, exerts profound influences on the initiation and progression of human cancers." (PMID 35111955, 2022). "Collectively, by identifying the VDR/VitD/BIM axis, we here provide a molecular rationale for the anti-cancer activity of VitD/analogs in combination therapies, which should be further exploited in clinics." (PMID 36291915, 2022).
cancer (continued). "Collectively, our study indicated that the VDR and CYP24A1 were broadly expressed in bone metastases of breast, prostate, renal, gastro-intestinal, follicular thyroid and other cancers." (PMID 36362766, 2022). "This revealed a set of genes shared with human eTreg cells from affected sites in JIA, RA, and cancer including BATF, VDR, MICAL2, TOX2, KAT2B, PFKFB3, and IL12Rβ2." (PMID 33976194, 2021). "Apart from VDR expression, enzyme CYP27B1 is also produced, so the cancer cell is capable of generating ligands for VDR." (PMID 33440610, 2021). "The discovery of the nuclear vitamin D receptor (VDR) and the demonstration of its presence in cancer cells gave rise to research into the role of vitamin D in the development and course of cancer." (PMID 33572090, 2021). "Ablation of VDR in injected tumor cells promoted EMT, cancer cell mobility (migration), and invasiveness, thereby facilitating skeletal colonization." (PMID 34950835, 2021). "A wide variety of cells including gut epithelia, immune cells, and cancer cells express both CYP27B1 and VDR, which provides the molecular basis for 1,25(OH)2D to exert its multifunctional role in the human body." (PMID 34072725, 2021). "The vitamin D receptor (VDR), primarily known as a crucial mediator of calcium homeostasis and metabolism, has been shown to play a significant role in various cancer entities." (PMID 32572587, 2020). "In the present study, we explored the relationship between VDR expression and STAT3 phosphorylation in PTC patients, as well as investigated the adjuvant anti‐cancer activity of Calcitriol and its potential mechanisms." (PMID 32285621, 2020). "In vivo and in vitro studies supported the role of vitamin D. The discovery that vitamin D receptors (VDR) could be identified in many cells other than the skeleton reinforced the conclusion that this vitamin had other far-reaching effects on autoimmunity and cancer." (PMID 31452062, 2020). "Gonzalo’s lab demonstrated that 1,25(OH)2D stabilized TP53BP1 via its interaction with VDR and promoted DSBR through the inhibition of CTSL, which is important in cancer progression and is involved in TP53BP1 degradation." (PMID 32456160, 2020). "In these networks, PTGS2, VDR, RHOB, PIM1, HSPA1L, HSPA1A, and SPHK1 were used as targets for cancer drug development, previously." (PMID 30842898, 2019). "Out of these, RHOB, VDR, and PTGS2 were the only candidates with FDA-approved anti-cancer drugs, with one each for RHOB and VDR, and 20 for PTGS2." (PMID 30842898, 2019). "First, snail family transcriptional repressor (Snail) that is overexpressed in several cancers and involved in EMT, tumor invasion, and metastasis was shown to inhibit VDR expression in cancer." (PMID 29657326, 2018). "Accumulating evidence suggests that VDR binds to PI3K, an upstream effector of AKT, and activates the PI3K-AKT signaling pathway in cancer cells." (PMID 29865262, 2018). "Consistently, amounting evidence has indicated the correlation of the Vitamin D Receptor (VDR) and cancer." (PMID 28489590, 2017). "The in vitro growth curves of PC3 cells exhibited similar results to those seen with MDA-MB-231 cells: Knockdown of VDR expression significantly reduced PC3 cell growth, while at the same time stimulating cancer cell apoptosis." (PMID 28944088, 2017). "In ligand-free culture, knockdown of VDR in MCF-7 cells significantly reduced proliferation and increased apoptosis, suggesting that the VDR plays a ligand-independent role in cancer cell growth." (PMID 28460457, 2017). "Such treatment of cancer cells also induces the activation of p38 and JNK that results in an upregulation of VDR expression." (PMID 26950144, 2016). "The functional interactions between AR and VDR, as well as other nuclear receptors and TFs may also be important for disease management, especially now that nutritional intervention has become more widely accepted as an effective approach to prevent cancer progression." (PMID 24860512, 2014).
cancer (continued). "The genomic pathway requires the binding of 1,25(OH)D3 to the vitamin D receptor (VDR), which regulates transcription of genes involved in numerous cellular processes relevant for anti-cancer effects." (PMID 24949795, 2014). "Vitamin D receptor (VDR) is a crucial mediator for the cellular effects of vitamin D and additionally interacts with other cell-signaling pathways that influence cancer development." (PMID 25541958, 2014). "VDR and CYP27B1 expression in mammary adipocytes also contribute to the anti-cancer effects in the whole tissue, since in response to 25(OH)D adipocytes secrete diffusible signals that inhibit morphogenesis of the adjacent ductal epithelium." (PMID 24982636, 2014). "In other types of cancer, e.g., the choriocarcinoma-derived trophoblast cell lines JEG-3 and JAR, the VDR promoter was densely methylated." (PMID 24808866, 2014). "1,25(OH)2D3 regulates gene expression via binding to the vitamin D receptor (VDR), a member of the superfamily of nuclear receptors that is expressed in many normal and cancer cell types." (PMID 24202444, 2013). "Data from 105 cancer patients on CYP27B1, VDR, CYP24A1, and COX-2 mRNA expression in relation to tumor grade, anatomical location, gender and age were fit into a multivariate model of exploratory factor analysis." (PMID 24213465, 2012). "The VDR growth regulatory equilibrium involving E-cadherin and OPN is disturbed during stepwise evolution of many human cancers although there are important tissue-specific differences." (PMID 19737544, 2010). "The vitamin D receptor (VDR) pathway is important in the prevention and potentially in the treatment of many cancers." (PMID 19924301, 2009). "The vitamin D endocrine system, consisting of the steroid vitamin D, the vitamin D receptor (VDR) and the metabolizing enzymes, plays an important role in skeletal metabolism, OA, the immune response, and cancer." (PMID 16507122, 2006). "The expression levels of the vitamin D receptor (VDR) and other genes involved in vitamin D signaling are increased in malignant thyroid cells, suggesting a potential anti-tumor response of vitamin D in cancer." (PMID 40778274, 2025). "Although there is growing evidence of cytological and animal studies supporting the suppressive role of VDR in cancers, the conclusion is still controversial in human cancers and no systematic pan-cancer analysis of VDR is available." (PMID 38639057, 2024). "To date, no pan-cancer analysis of the relationship between VDR and human cancers has been performed." (PMID 38639057, 2024). "The mutual heterodimers of RXRB and vitamin D receptor (VDR) promoted the development of cancer, and activated the Ras-Raf-MAPK-ERK signaling pathway to involve in the dominating VDR pathway for various gene expressions regulation (Deeb, Trump & Johnson, 2007)." (PMID 39465162, 2024). "Here, we highlight that, downstream of VDR, small molecule activators for SIRT1 such as SRT1720 offer an alternative approach and a therapeutic hope for these cancers if they could be directed specifically to cancer cells." (PMID 39494323, 2024). "Due to space issues, we summarize three important VDR-dependent non-communicable diseases (Cancer, cardiometabolic disorders, and bone diseases) that are particularly important for our subsequent session discussion below." (PMID 38318147, 2024). "The associations found are likely due to the broader role of the VDR gene in cancer biology, rather than being specific to GC." (PMID 39213223, 2024). "In conclusion, VDR is a potential prognostic biomarker and positively correlated with immune infiltration as well as stromal or immune components in TME in multiple human cancers." (PMID 38639057, 2024). "Finally, the proposed method identified a subnetwork that included a well-known cancer gene FOXA1 and four genes from the Vitamin D receptor pathway, which suggests a potentially functional connection." (PMID 37627118, 2023).